Y_RNA (Y RNA )
Gene: Miscellaneous RNA gene on chromosome 2 (232,828,653 to 232,828,751, forward strand). Ensembl gene ENSG00000199781.
Homologues: Orthologues: chimpanzee Y_RNA (100% identical), guinea pig Y_RNA (79% identical), macaque Y_RNA (77% identical). Paralogues in human: RNY4 (85% identical), RNY4P29 (82% identical), RNY4P6 (82% identical), RNY4P9 (82% identical), Y_RNA (82% identical), RNY4P17 (81% identical), RNY4P3 (81% identical), Y_RNA (81% identical), RNY4P14 (80% identical), RNY4P7 (80% identical), Y_RNA (80% identical), RNY4P19 (79% identical), and 90 more.